CBS (cystathionine beta-synthase)
Diseases named in the same sentence as CBS in open-access papers (continued):
Sharing a sentence is not in itself a finding about the gene and the disease.
arteriosclerosis (1 paper, 2019). A vascular disorder characterized by thickening and hardening of the walls of the arteries. "In CBS+/− kidney sections stained with picrosirius red, there was increased type I collagen in the interlobular arteries suggesting arteriosclerosis (yellow arrow)." (PMID 30778103, 2019).
asthma (1 paper, 2025). "CYBB (AUC ═ 0.82), EPAS1 (AUC ═ 0.839), CBS (AUC ═ 0.804), G6PD (AUC ═ 0.86), and STAT3 (AUC ═ 0.873) demonstrate high diagnostic accuracy for asthma (AUC > 0.8)." (PMID 40165005, 2025). "In conclusion, CYBB, EPAS1, CBS, G6PD, and STAT3 demonstrate strong diagnostic potential for asthma." (PMID 40165005, 2025). "Our investigation also identified important genes involved in ferroptosis and asthma, including EPAS1, STAT3, G6PD, CYBB, and CBS." (PMID 40165005, 2025).
atopic dermatitis (1 paper, 2020). "The possible effects of increased CBS and MRRF activity might offer therapeutic value to atopic dogs, since ROS production is increased in canine atopic dermatitis during the inflammatory process." (PMID 33178726, 2020).
bone cancer (1 paper, 2014). A primary or metastatic malignant neoplasm affecting the bone or articular cartilage. "However, expression of CBS was not altered in the rat model of sciatic nerve injury model and bone cancer pain model (personal unpublished data), suggesting a disease-specific upregulation of CBS expression." (PMID 24490955, 2014).
brain tumors (1 paper, 2022). "Despite the remarkable number of studies that link H2S disturbances and oncogenesis, few studies are dedicated to identifying the expression level of CBS in human brain tumors and its association with disease progression." (PMID 36358663, 2022). "The targeting of CBS has been a tremendous challenge in several contexts, including several solid malignancies, such as brain tumors." (PMID 36358663, 2022). "Nevertheless, the spatial distribution of CBS, CSE, and 3MST in the brain and their correlation with brain tumors are still unclear and should be investigated further to understand their contribution to brain oncogenesis." (PMID 36358663, 2022). "It was generally clear that CBS is downregulated, whereas CSE and 3MST are upregulated and directly correlated with the brain tumor grade reaching the highest expression level at grade III; then, CSE and 3MST start to drop in their expression levels at later grades." (PMID 36358663, 2022).
cerebral infarction (1 paper, 2020). An ischemic condition of the brain, producing a persistent focal neurological deficit in the area of distribution of the cerebral arteries. "In summary, our study found that hypomethylation of the CBS promoter region is a risk factor for cerebral infarction and it can serve as a potential biomarker for the diagnosis of cerebral infarction." (PMID 33138824, 2020). "Our goal is to assess whether promoter methylation of AHCY and CBS can be used as a diagnostic biomarker for the risk of cerebral infarction." (PMID 33138824, 2020). "Our study suggests that hypomethylation of the CBS promoter may be closely related to the risk of cerebral infarction and may be used as a non-invasive diagnostic biomarker for cerebral infarction." (PMID 33138824, 2020). "Our results indicated that hypomethylation in the CBS promoter region was significantly associated with cerebral infarction and might serve as a potential biomarker for the diagnosis of cerebral infarction." (PMID 33138824, 2020). "The goal of our study is to investigate whether the methylation levels of AHCY and CBS promoters are related to the risk of cerebral infarction by detecting the methylation level of AHCY and CBS genes." (PMID 33138824, 2020). "Specifically, we found that 73.0% (111/152) of the 152 patients with cerebral infarction had hypomethylation of the CBS gene promoter region in contrast to only 30.0% (46/152) of the 152 healthy controls." (PMID 33138824, 2020). "In this study, we examined the relative methylation levels of the AHCY and CBS genes in 152 patients with cerebral infarction and 152 healthy controls." (PMID 33138824, 2020). "In this study, we examined the levels of AHCY and CBS promoter methylation in peripheral blood from patients with cerebral infarction and healthy controls." (PMID 33138824, 2020). "We compared the promoter methylation levels of two genes (AHCY and CBS) in peripheral blood DNA between the cerebral infarction case group and the control group." (PMID 33138824, 2020). "This indicated that CBS hypomethylation might be used as a potential biomarker for the diagnosis of cerebral infarction." (PMID 33138824, 2020). "Usually, insufficient methylation will lead to overexpression of genes, but our research shows that the CBS gene in the case group is in a state of insufficient methylation, there is no functional mechanism linking the CBS gene hypomethylation to cerebral infarction." (PMID 33138824, 2020). "Therefore, methylation of the CBS promoter region can be used as a potential biomarker for diagnosing cerebral infarction." (PMID 33138824, 2020). "We extracted peripheral venous blood from 152 patients with cerebral infarction and 152 gender- and age-matched healthy controls, and determined methylation levels of AHCY and CBS promoters using quantitative methylation-specific polymerase chain reaction." (PMID 33138824, 2020).
Cerebral ischemia (1 paper, 2020). Restriction of arterial blood supply to the brain associated with insufficient oxygenation to support the metabolic requirements of the tissue. "The results were in accordance with previous reports that the expression of CBS and concentration of H2S increased in the hippocampus of rats after brain ischemia, it indicated that hydrogen up-regulated the H2S levels in ischemic brain, and H2S could reduce cerebral I/R injury in the animal model." (PMID 32489564, 2020).
cerebral malaria (1 paper, 2020). A sequestration of Plasmodium falciparum in the brain, which can cause coma and/or seizures. "In experimental cerebral malaria characterized by blood leakage into the brain, CBS expression and H2S bioavailability are low, which is associated with the damage of the blood-brain barrier, suggesting that a low brain H2S level may contribute to the pathology of experimental cerebral malaria." (PMID 33374506, 2020).
choriocarcinoma (1 paper, 2024). An aggressive malignant tumor arising from trophoblastic cells. "In addition, one patient was diagnosed with cystathionine beta-synthase deficiency, another with hypertrophic duraitis, one with concomitant choriocarcinoma, and one with intracranial infection." (PMID 38886735, 2024).
chronic gastritis (1 paper, 2021). Inflammation of the stomach that is chronic in nature. "Notably, the GIM-GC common CIMP signature again included aberrant CBS promoter hypermethylation (average β-value difference = 0.28 between GIM CIMP compared to chronic gastritis in antrum, P < 0.05), indicating its early occurrence in the pre-cancerous GC cascade." (PMID 34074348, 2021).
colon adenocarcinoma (1 paper, 2023). "Kaplan–Meier curves show that although generally low CBS expression is associated with colon adenocarcinoma, reduced overall survival is significantly (p=0.017) associated with high CBS expression." (PMID 37483514, 2023). "From the long-term survival, it is apparent that low CBS expression affects rectal carcinoma rather than colon adenocarcinoma." (PMID 37483514, 2023).
colorectal tumor (1 paper, 2022). "In colorectal tumor tissue and cancer-derived cell lines, the expression of CBS is upregulated and closely related to tumor growth and carcinogenesis." (PMID 35172821, 2022).
COVID-19 (1 paper, 2025). A disease caused by infection with severe acute respiratory syndrome coronavirus 2. "Virus replication is associated with down-regulation of the H2S-producing enzymes cystathionine-β-synthase (CBS), cystathionine-γ-lyase (CTH), and 3-mercaptopyruvate sulfurtransferase (3-MST) in multiple cell lines and nasopharyngeal swabs of symptomatic COVID-19 patients." (PMID 40388397, 2025).
cyst (1 paper, 2024). A sac-like closed membranous structure that may be empty or contain fluid or amorphous material. "Indeed, in vitro, knockdown of CBS exacerbated the reduced cell viability and increased lipid peroxide accumulation induced by the addition of cyst(e)inase to the culture medium." (PMID 38490069, 2024).
cystathioninuria (1 paper, 2019). Cystathioninuria is an autosomal recessive disorder caused by cystathionine gamma-lyase deficiency. "Therefore, patients with silent CTH-deficient cystathioninuria that exist with a low but substantial frequency should be carefully examined; CBS deficiency had been detected with a frequency between 1:200,000 and 1:335,000." (PMID 31319489, 2019).
cystitis (1 paper, 2025). Inflammation of the urinary bladder. "Inhibition of the major H2S-synthesizing enzymes CSE and CBS by their inhibitors PAG and AOAA abrogated the protective effects of DR on CYP-induced cystitis." (PMID 40432898, 2025).
diabetic nephropathy (1 paper, 2024). "Recent research demonstrated that exercise training increased the expression of CBS/CSE and enhanced endogenous H2S production in the renal tissues of diabetic nephropathy." (PMID 39895674, 2024).
disc degeneration (1 paper, 2018). "Interestingly, the authors found advanced disc degeneration was accompanied with reduced CBS and CSE expression." (PMID 29466396, 2018).
dissection (1 paper, 2022). The separation and isolation of tissues for surgical purposes, or for the analysis or study of their structures. "CBS encoding cystathionine-beta-synthase, has been categorized as a low-risk gene for aortic dissection." (PMID 36561772, 2022).
Duchenne muscular dystrophy (1 paper, 2025). Duchenne muscular dystrophy (DMD) is a neuromuscular disease characterized by rapidly progressive muscle weakness and wasting due to degeneration of skeletal, smooth and cardiac muscle. "Gene transcript levels of CSE, CBS and 3‐MST were also reduced in Duchenne muscular dystrophy (DMD), indicating that diminished endogenous H2S production may contribute to DMD pathogenesis." (PMID 41030226, 2025).
embryonal carcinoma (1 paper, 2024). A non-seminomatous malignant germ cell tumor characterized by the presence of large germ cells with abundant cytoplasm resembling epithelial cells, geographic necrosis, high mitotic activity, and pseudoglandular and pseudopapillary structures formation. "On the other hand, excessive expression of CBS and CSE in the oviducts may be a sign of ectopic gravidity or embryonal carcinoma, so it cannot be conclusively stated that higher levels of CBS and CSE expression in this tissue indicate physiological embryo transport." (PMID 38933705, 2024).
endotoxemia (1 paper, 2018). "In LPS-treated mice the findings of indicated that a deficiency in MPST does not significantly affect endotoxemia but a deficiency in CBS or CSE slightly ameliorates the outcome of LPS-induced endotoxemia in vivo." (PMID 30386265, 2018).
fibrosis (1 paper, 2019). the formation of excess fibrous connective tissue in an organ or tissue in a reparative or reactive process. "We found increased collagen deposition in the left ventricle of CBS+/− mice by picosirius red, which stains all types of collagen indicating increased cardiac fibrosis." (PMID 31178749, 2019).
gallbladder adenocarcinoma (1 paper, 2021). A carcinoma that arises from glandular epithelial cells of the gall bladder. "Positive CBS is closely associated with a decreased overall survival in patients with gallbladder squamous cell carcinomas or gallbladder adenocarcinomas." (PMID 34970597, 2021).
gallbladder cancer (1 paper, 2020). "A study has suggested that positive CBS is associated with the clinical severity and poor prognosis in gallbladder cancer." (PMID 32701483, 2020).
hematoma (1 paper, 2023). A hematoma is a collection of blood from a vascular structure into an extravascular space. "Notably, endogenous H2S derived from CBS in microglia promoted continual phagocytosis of erythrocytes by microglia in vitro and contributed to spontaneous hematoma resolution at 5 days and 14 days following ICH in a mouse model." (PMID 37601043, 2023).
hepatic porphyria (1 paper, 2021). A group of metabolic diseases due to deficiency of one of a number of liver enzymes in the biosynthetic pathway of heme. "The hypothesis predicts likely changes in CBS activity and plasma Hcy levels in untreated hepatic porphyria patients and in those receiving hemin or certain gene-based therapies." (PMID 34251022, 2021).
Hermansky-Pudlak syndrome 2 (1 paper, 2025). A type of Hermansky-Pudlak syndrome (HPS), a multi-system disorder characterized by oculocutaneous albinism, bleeding diathesis and neutropenia. "Sperandeo reports a patient from Spain with CBS, c.869C>T variant in exon 8 with associated, Hermansky Pudlak syndrome 2 (characterised by oculocutaneous albinism and clotting abnormalities), and pyridoxine responsiveness." (PMID 39839200, 2025).
Hypercholesterolemia (1 paper, 2020). An increased concentration of cholesterol in the blood. "Although the precise mechanism responsible for the increased CBS expression at the cell surface remains elusive, hypercholesterolemia appears to disrupt a negative feedback desensitization response that downregulates CBS in response to IL3 or GM-CSF stimulation." (PMID 32086626, 2020).
Hyperkeratosis (1 paper, 2020). Hyperkeratosis is a histopathological term defining a thickened stratum corneum and may be present in many different skin conditions, with many possible overlaps. "Biological functions activated by CBS included for example concentration of glutathione, conversion of homocysteine, and concentration of phospholipids, and inhibited by CBS included for example oxidative stress, hyperkeratosis, and accumulation of reactive oxygen species." (PMID 33178726, 2020).
hypothyroidism (1 paper, 2017). Abnormally low levels of thyroid hormone. "Finally, we confirmed that T3 alone, without the induction of hypothyroidism via a PTU/LID, reduced hepatic CGL and CBS mRNA, correlating with protein levels, hepatic H2S production capacity and characteristic changes in hepatic metabolites, including cystathionine and cysteine." (PMID 28591635, 2017).
infantile epilepsy (1 paper, 2025). "At the protein level, western blots validated expression changes in CBS (mental retardation), NEAS/SPTAN1 (associated with infantile epilepsy), FBLN1 (cardiac morphogenesis), FXR1 (muscle development), and SHANK2 (neuronal differentiation in the retina)." (PMID 39508990, 2025).
injury (1 paper, 2025). Damage inflicted on the body as the direct or indirect result of an external force, with or without disruption of structural continuity. "For example, exogenous H2S restored CBS and CSE enzyme expression in the hypothalamus 28 days after traumatic brain injury." (PMID 40551819, 2025).
intracranial hypertension (1 paper, 2019). A finding characterized by increased cerebrospinal fluid pressure within the skull. "A 9-year-old CBS-deficient B6 non-responder male patient treated with 6 g/day of betaine anhydrous (initiated after the start of the event) experienced brain vein thrombosis which led to brain oedema and intracranial hypertension." (PMID 30871635, 2019).
keloid (1 paper, 2025). An irregularly shaped, elevated mark on the skin caused by deposits of excessive amounts of collagen during wound healing. "Heat maps showed decreased expression of genes involved in Hcy catabolism, including CBS, MTR, 5-methylenetetrahydrofolate homocysteine methyltransferase reductase (MTRR), methylenetetrahydrofolate reductase (MTHFR), and methionine adenosyltransferase 1a (MAT1A) in keloids." (PMID 39919369, 2025).
kidney injury (1 paper, 2014). Trauma to the kidney. "Our results, for the first time, suggest that downregulation of CBS and CSE mediated H2S and glutathione production contributes to the pathogenesis of I/R‐induced kidney injury." (PMID 25539831, 2014).
learning disorders (1 paper, 2022). "Consistent with this, our transcriptome analysis revealed a decrease in the expression of the following genes that may be responsible for the observed STM and learning disorders in strains with CBS deletions, and especially in the case of double deletions: pka-c1, eag, Sh, and cac." (PMID 35740876, 2022).
leukodystrophies (1 paper, 2023).
Li-Fraumeni syndrome (1 paper, 2010). "Three genetic diseases in which missense mutations are common include cystathionine β-synthase (CBS) deficiency, Li Fraumeni syndrome, and methylenetetrahydrofolate reductase deficiency." (PMID 20066033, 2010).
lupus (1 paper, 2023). "In MRL/lpr mice, CSE and CBS mRNA levels were decreased with the lupus progress as evidenced by the fact that they were further reduced at 16 weeks old compared with 8 weeks old." (PMID 36829595, 2023). "Consistently, we found that an H2S donor could increase CSE and CBS expression in the renal tissues of lupus mice." (PMID 36829595, 2023). "CSE and CBS mRNA levels were significantly reduced in the kidney of 16-week-old MRL/lpr mice, pristane-induced lupus mice, and R848-induced lupus mice, even though the expression in pristane-induced mice showed no significance." (PMID 36829595, 2023). "CSE and CBS mRNA levels were reduced in MRL/lpr and pristine- and R848-induced lupus mice." (PMID 36829595, 2023). "Of note, the present study showed that the expression pattern of CBS and CSE were not consistent in three animal models of lupus." (PMID 36829595, 2023).
malaria (1 paper, 2017). Malaria is a serious and sometimes fatal disease caused by a parasite that commonly infects a certain type of mosquito which feeds on humans. "Our bioinformatics analysis of genes coding for the enzymes involved in the transsulphuration pathway of malaria parasite revealed the absence of two key enzymes in the biosynthesis of cysteine from homocysteine, namely CBS and CGL." (PMID 28091526, 2017). "Absence of CBS would preclude synthesis of cystathionine in the malaria parasite." (PMID 28091526, 2017).
malnutrition (1 paper, 2017). Inadequate nutrition resulting from poor diet, malabsorption, or abnormal nutrient distribution. "In this complex metabolic scenario, the liver uses the structural and functional versatility of the CBS enzyme to maintain a balance between a multitude of distinct, divergent, and sometimes opposite impulses, in particular, when malnutrition and inflammatory influences coexist." (PMID 28930162, 2017).
Methylmalonic aciduria (1 paper, 2023). Increased concentration of methylmalonic acid in the urine.
migraine (1 paper, 2017). "We suggest that up-regulation of CSE or CBS during migraine related neuro-inflammation in meninges generates H2S resulting in activation of pro-nociceptive TRPV1 and TRPA1 receptors." (PMID 28798669, 2017).